ATR (ATR checkpoint kinase)
Diseases named in the same sentence as ATR in open-access papers (continued):
Sharing a sentence is not in itself a finding about the gene and the disease.
glioblastoma (continued). "In summary, we present a novel role for ATR in regulating glioblastoma invasion which, in addition to furthering our understanding of the mechanisms underpinning glioblastoma invasion, has significant relevance for clinical translation." (PMID 37936324, 2024). "In glioblastoma, ATR can reduce the cytotoxic effects of TMZ or RT by signalling the repair of treatment induced SSBs and DSBs." (PMID 38227740, 2024). "Overall, our study provides preliminary evidence that ATR inhibition induces a proinflammatory response within glioblastoma cells and warrants further investigation." (PMID 38227740, 2024). "We demonstrate that this function of ATR is highly sensitive to pharmacological inhibition, resulting in abrogation of glioblastoma invasion both in vitro and in vivo, and presents a novel clinical approach to disease management." (PMID 37936324, 2024). "Glioblastoma motility and invasion were assessed in vitro and in vivo in response to ATR inhibition (ATRi) and ATR overexpression using time-lapse microscopy, two orthotopic glioblastoma models, and intravital imaging." (PMID 37936324, 2024). "Lastly, ATR inhibition alters the gene expression of innate immune and inflammatory signalling pathways within glioblastoma cells, which requires additional validation and investigation as a strategy to provoke an immunomodulatory response." (PMID 38227740, 2024). "Altogether, our results reveal an immune-modulatory effect after ATR inhibition in glioblastoma cells." (PMID 38227740, 2024). "We showed in glioblastoma cells that therapeutically relevant doses (<50 μM) of TMZ are effective in activating the ATR/ATM-SIAH1/HIPK2-p53Ser46 axis and thus trigger apoptosis." (PMID 38068493, 2023). "MYC-induced repression of CDK18, as well as ATR inhibition, affects ATR activity, and increases sensitivity to PARPi, thus representing a promising therapy for glioblastoma and, potentially, other PARPi-refractory tumors." (PMID 34201047, 2021). "Based on our data, further clinical development steps of ATR inhibitors should include glioblastoma with high bHLH expression." (PMID 33134924, 2020). "Here, the authors show that MYC amplified glioblastomas are sensitive to PARP inhibition due to CDK18 repression, which impairs ATR regulated homologous recombination repair, and that ATR inhibition sensitises glioblastomas to PARP inhibition." (PMID 31266951, 2019). "In our study, we found that knockdown of MINA53 decreased not only the expression of ATM and ATR but also their phosphorylation pattern in glioblastoma cells." (PMID 30333481, 2018). "We show that single agent ATR inhibition is more sensitive in tumours with higher cell cycle gene expression and an increased frequency of DDR mutations, as well as more sensitive in MGMT unmethylated and TMZ+RT resistant glioblastoma." (PMID 38227740, 2024). "Overall, this data shows gartisertib to be a potent ATR inhibitor, especially in MGMT promoter unmethylated glioblastoma cell lines, in which DDR gene mutations and higher expression of cell cycle genes/pathways associated with greater sensitivity to ATR inhibition." (PMID 38227740, 2024). "This suggests that ATR inhibition combined with chemoradiation may be more effective in glioblastoma cells displaying an inflammatory and potentially more aggressive phenotype." (PMID 38227740, 2024). "We demonstrate a novel role for ATR in determining invasion in glioblastoma cells and propose that pharmacological targeting of ATR could have far-reaching clinical benefits beyond radiosensitization." (PMID 37936324, 2024). "Time-lapse imaging of treated glioblastoma cells revealed a deadhesion/retraction defect at the termini of neurite structures upon ATR inhibition, resulting in their increasing lengthening and fragility over time, leading to destabilization and ultimately breakage." (PMID 37936324, 2024).
glioblastoma (continued). "We present data that describe a novel, noncanonical role for ATR kinase in facilitating tumor cell motility and invasion via macropinocytic internalization of integrins and identify ATR as a readily translatable target to achieve containment of disease dissemination in glioblastoma." (PMID 37936324, 2024). "Using a panel of 12 patient-derived glioblastoma cell lines, we investigated the chemo- and radio-sensitising effect of gartisertib, a potent and selective inhibitor of ATR that was explored in a phase 1 clinical trial for patients with advanced solid tumours (NCT02278250)." (PMID 38227740, 2024). "Next, we analysed the baseline molecular profile of the 12 glioblastoma cell lines to explore the relationship between ATR inhibition sensitivity and molecular features such as MGMT methylation, single nucleotide polymorphisms (SNVs) and pathway gene expression." (PMID 38227740, 2024). "Using in vitro and in vivo studies and 4 different primary glioblastoma lines, we report a novel role for ATR in driving the invasion of glioblastoma cells via the regulation of actin and microtubule networks that support turnover of integrins at growth-cone-like structures." (PMID 37936324, 2024). "Overall, this study identifies ATR inhibition as a strategy to enhance the DNA-damaging ability of glioblastoma standard treatment, while providing preliminary evidence that ATR inhibition induces an innate immune gene signature that warrants further investigation." (PMID 38227740, 2024). "A detailed analysis of the data from The Cancer Genome Atlas (TCGA) consortium set for glioblastoma multiforme (GBM), the most common and lethal primary central nervous system tumor in adults, shows that 3.2% of tumours have somatic mutations in ATR, ATM, or CHK1." (PMID 25247188, 2014). "STAG2 deficient glioblastoma and Ewing sarcoma cells are more sensitive to DNA alkylating agents, DNA crosslinking agents, topoisomerase inhibitors, Poly (ADP-ribose) polymerase (PARP) inhibitors, and ataxia telangiectasia and Rad3-related protein (ATR) inhibitors." (PMID 40025053, 2025). "In glioblastoma cells, ART was shown to induce oxidative DNA damage and DNA double-strand breaks that accumulate during the treatment period and finally activate the ATM/ATR axis and DNA damage-dependent pathways causing cell cycle inhibition and apoptotic cell death." (PMID 40564198, 2025). "Here, we investigated the activity of gartisertib, a potent ATR inhibitor, alone and in combination with TMZ and/or RT in 12 patient-derived glioblastoma cell lines." (PMID 38227740, 2024). "On the other hand, targeting DDR through ATR inhibition directly enhances the DNA damaging abilities of treatments such as TMZ or RT and is therefore more synergistic across different glioblastoma cell lines." (PMID 38227740, 2024). "The role of MYC as a sensitizer to PARPi-based therapy is also reported in patient-derived glioblastoma stem-like cells (GSCs), which show MYC or MYCN amplification and are more sensitized to PARPi when ATR activity is pharmacologically inhibited." (PMID 34201047, 2021). "We showed that ATR inhibition using gartisertib significantly reduced cell growth and increased markers of apoptosis and cell death when combined with TMZ and RT across the glioblastoma cell lines." (PMID 38227740, 2024). "Interestingly, CDK18 also plays a role in ATR-mediated Homology-Directed Repair (HDR), in glioblastoma." (PMID 38951876, 2024). "Besides, CDK18 facilitates ATR activation by interacting with ATR and regulating ATR-Rad9/ATR-ETAA1 interactions, promoting HR and PARPi resistance in glioblastoma stem-like cells." (PMID 32563252, 2020). "To assess cellular toxicity to a single or combined treatment of PARP1 inhibitor (Olaparib; 10nM, 1μM and 10μM) and/or ATR inhibitor (AZD6738; 0.5μM; 1μM, 10μM and 20μM), we performed clonogenic survival assays using two different glioblastoma cell lines (LN428 and LN18)." (PMID 29348879, 2017).
glioblastoma (continued). "Considering the lack of benefit from ICI therapies within glioblastoma due to low immune infiltrates, the stimulation of innate immune response and antigen presentation through ATR inhibition is a potential therapeutic strategy that could synergise with current anti-PD1/PD-L1 inhibitors." (PMID 38227740, 2024). "Inhibition of ATR by AZD-6738 resulted in robust and dose-dependent radiosensitization of glioblastoma cells, whereas LIG4 inhibition by L189 had no noticeable impact." (PMID 35440003, 2022).
ataxia telangiectasia (29 papers, 2005 to 2026). Ataxia-telangiectasia is the association of severe combined immunodeficiency (affecting mainly the humoral immune response) with progressive cerebellar ataxia. "ATR-Chk1 dysfunction is associated with a large number of DNA damage and chromosomal rearrangements in Ataxia-telangiectasia (A-T) patients, especially in lymphocytes, which often leads to the production of fusion genes." (PMID 36998465, 2023). "Key checkpoint players include the apical protein kinases Tel1 and Mec1, whose mammalian orthologs are ATM (ataxia telangiectasia mutated) and ATR (ataxia telangiectasia and Rad3-related), respectively." (PMID 36291091, 2022). "It becomes activated by the phosphatidylinositol 3-kinase-like serine/threonine kinases ATR (ataxia telangiectasia response) and ATM (ataxia telangiectasia mutated) through phosphorylation of Ser-317 and Ser-345 followed by autophosphorylation of Ser-296." (PMID 23483975, 2013). "This family of protein kinases also includes ATM, the gene product that is mutated in the autosomal recessive disorder ataxia telangiectasia (AT), ATR, and DNA-dependent protein kinase (DNA-PK)." (PMID 19384426, 2007). "Recently, we have shown that nitric oxide inhibits DDR signaling (ATM, ataxia telangiectasia mutated and ATR, ataxia telangiectasia and Rad3-related) by a mechanism that is associated with the inhibition of mitochondrial oxidative metabolism and decreases in cellular levels of ATP." (PMID 38586887, 2024). "Their parents, heterozygous carriers of pathogenic ATR variants, should also be monitored for cancer predisposition as it is done for heterozygous carriers of ATM pathogenic variant that cause ataxia-telangiectasia in a homozygous state." (PMID 36749285, 2023). "Patients will receive a combination of lurbinectedin and berzosertib, an ataxia telangiectasia and Rad3-related (ATR) protein kinase inhibitor." (PMID 36110944, 2022). "Among the 12 validated candidates in our siRNA screen, the most potent and robust SEL target was the ATR gene (Ataxia-telangiectasia and the Rad3-related kinase)." (PMID 35178190, 2022). "MRE11, together with RAD50 and NBS1 (MRE11-RAD50-NBS1 complex), locates to the end of the double-strand breaks (DSBs) locus and activates ATM through the interaction between ATM and NBS1, triggering ataxia telangiectasia and ATR activation." (PMID 34917121, 2021). "In particular, ataxia telangiectasia and Rad3-related (ATR)-CHK1 signal cascades are the main factors of replication stress response." (PMID 33424998, 2020). "To further examine synapsing efficiency in ATZ-treated mice, we stained chromosomes with an antibody against ATR (ataxia telangiectasia and Rad3-related), a marker of asynapsed chromosomes and silenced chromatin." (PMID 26518232, 2015). "PP2A is known to maintain a regulatory circuit with checkpoint kinase Chk1 by continuously dephosphorylating Chk1 which is itself continuously phosphorylated by ATR (Ataxia-telangiectasia-related)." (PMID 25012639, 2014). "Loss of ATM activity, either by genomic mutation (ATM-deficient fibroblasts from an ataxia telangiectasia patient) or by administration of a chemical inhibitor (AAI, an inhibitor of ATM and ATR), blocks IGF-1-sCLU expression in senescent cells." (PMID 24937130, 2014). "Similar to observations in ATM-inhibited or ataxia-telangiectasia cells exposed to DNA damaging agents, these results suggest that ATR and DNA-PKcs may cross-phosphorylate substrates of ATM during SV40 infection." (PMID 25474690, 2014). "It has been shown that CDK18 may be involved in Alzheimer’s disease, in the Ataxia Telangiectasia and RAD3-related (ATR)-mediated response to single strand DNA and in cell cycle control." (PMID 32164329, 2020).
ataxia telangiectasia (continued). "Using both plasmid and adeno-associated virus (AAV) donor vectors, our results demonstrate that ataxia telangiectasia and Rad3-related kinase (ATR) activity is essential for knock-in regardless of the donor type, whereas ataxia telangiectasia mutated (ATM) inhibition exhibits a donor-dependent role." (PMID 41651998, 2026).
colon carcinoma (29 papers, 2009 to 2025). "For instance, knockdown of ATR impairs the stemness characteristics of colon cancer cells, suppressing their tumorigenic ability." (PMID 37349788, 2023). "Yet, similar effects were only observed in CD133+ colon carcinoma stem cells, where ATR inhibition abrogated the tumorigenicity of CD133+ CSC." (PMID 35280989, 2022). "Subsequently, the DDR pathway induced by the activation of ATM/ATR proteins is modulated in colon cancer cells." (PMID 32290112, 2020). "The expression of ATM in tumors located in rectum was lower compared to its adjacent mucosa, in contrast to ATR, which showed a significant increased expression in colon cancer relative to its adjacent mucosa." (PMID 29870526, 2018). "The first truly selective ATR inhibitor, VE-821, showed synergy with gemcitabine in human colon cancer cell lines." (PMID 28448462, 2017). "To study the mechanism involved in this process, we used tumors obtained from Apcmin/+ mice and human colon cancer cells and showed that a deficit in Ino80 induced replication stress, leading to the ATR-mediated activation of Chk1 and increased apoptosis." (PMID 29383140, 2017). "Our exploration of the mechanism underlying this effect suggested that Ino80 haploinsufficiency inhibited colon cancer tumorigenesis by activating replication stress-induced ATR-Chk1 signaling to increase apoptosis." (PMID 29383140, 2017). "The reports of the potent sensitizing effect of ATR inhibitors, including VE-821, on chemotherapy prompted us to assess the effect of the combination of ABT-888 and VE-821, targeting PARP and ATR, respectively, on irinotecan cytotoxicity in colon cancer cells." (PMID 26257651, 2015). "The parent DLD1 colon carcinoma cells and the ATR mutant knock-in cells, termed “DLD-ATR-Seckel” cells, were treated with one of several different agents and assayed for survival in clonogenic assays." (PMID 27713304, 2010). "It has been previously reported that ATR is activated in Geminin-depleted colon cancer cell lines." (PMID 34009124, 2021). "Therefore, we selected two colon cancer cell lines that are dependent on the ATR/Chk1 pathway, and observed that Chk1 phosphorylation levels gradually increased after HGF stimulation; this increase was not dependent on HGF concentration." (PMID 28573382, 2017). "Because we found that Ino80 depletion induced stalled replication forks, we next asked whether Ino80 activates ATR-Chk1 signaling in human colon cancer cells." (PMID 29383140, 2017). "In this study, we explored the role of HGF on the ATR/Chk1 pathway in colon cancer cells." (PMID 28573382, 2017). "ABT-888 and VE-821, inhibitors of poly-ADP-ribose-polymerase (PARP) and the serine/threonine-kinase Ataxia telangiectasia related (ATR), respectively, were used to treat colon cancer cell lines in combination with the topoisomerase-I inhibitor irinotecan (SN38)." (PMID 26257651, 2015). "ATR inhibitors (ATRi) exhibit synergy with cisplatin in killing HCT-116 colon cancer cells suggesting combinations of ATRi and cisplatin may be useful therapeutically." (PMID 25965342, 2015). "Other inhibitors, like KU-59403, specifically enhance the effects of topoisomerase poisons in colon cancer, while AZ31 and AZD0156, dual ATM/ATR inhibitors, exhibit synergy with chemotherapy in colorectal and triple-negative breast cancer." (PMID 40256842, 2025). "Jiangsu Hengrui Medicine (2022) patented an imidazopyrimidine derivative targeting ATR, DNA-PK, and PI3K, showing promise for colon cancer treatment." (PMID 40256842, 2025).
colon carcinoma (continued). "Analyses of publicly available gene expression data sets confirmed co-expression of MYB and ATR also in AML, adult T-ALL, and colon carcinomas and adenomas." (PMID 32001675, 2020). "The difference in ATR, ATM and Chk1 expression pattern between rectal and colon cancer strength that of considering colon and rectum are distinctive organs rather than one common entity, at least at the molecular level." (PMID 29870526, 2018). "Likewise, doxorubicin-treated breast, lung, and colon carcinoma cells undergo cellular senescence in vitro, which is characterized by a constitutively active ATM/ATR-dependent DNA damage response and the induction of p21." (PMID 21637851, 2011). "In contrast, the finding that disabling the ATR and BER pathways strongly sensitizes to FdUrd, indicates that this agent kills colon tumor cells primarily by affecting DNA metabolism, thus demonstrating that 5-FU and FdUrd have very different mechanisms of action." (PMID 22194930, 2011). "Notably, however, it remains unclear whether the ATR and/or ATM checkpoint pathways play important roles in determining the survival of human colon cancer cells, the cells that are targeted by 5-FU and FdUrd in patients, when they are treated with these agents." (PMID 22194930, 2011). "Notably, however, depletion of ATM or ATR does not sensitize colon cancer cells to 5-FU, whereas these checkpoint pathways promote the survival of cells treated with FdUrd, suggesting that FdUrd exerts cytotoxicity by disrupting DNA replication and/or inducing DNA damage, whereas 5-FU does not." (PMID 22194930, 2011). "Notably, analysis of global gene expression data sets revealed co-regulation of MYB and ATR also in other human malignancies such as for example AML, adult T-ALL, and colon carcinoma, indicating that the link between MYB and ATR is not restricted to ACC." (PMID 32001675, 2020).